HK2 (hexokinase 2)
Diseases named in the same sentence as HK2 in open-access papers (continued):
Sharing a sentence is not in itself a finding about the gene and the disease.
breast cancer (continued). "The oncogenic role of HK2 has been observed in other cancer conditions too, including gastric cancer, hepatocellular carcinoma, renal cell carcinoma, and in brain metastases of breast cancer." (PMID 29220380, 2017). "Moreover, we showed that miR-143 regulates cancer glycolysis in ZD-induced esophageal neoplasia by targeting HK2, a result consistent with reports for lung cancer, renal cell carcinoma, head and neck squamous cell carcinoma, breast cancer, and prostate cancer." (PMID 29137232, 2017). "Interestingly, it was recently reported that Prop inhibits glucose metabolism of breast cancer cells through ADRB2-dependent posttranscriptional downregulation of hexokinase-2." (PMID 27926515, 2017). "Interestingly, in breast cancer cells and renal cell carcinoma, hexokinase-2 (HK2) has been shown to be directly regulated by miR-143/145." (PMID 25383562, 2014). "For 2DG, an inhibitor of HK2, was shown that could overcoming trastuzumab resistance in breast cancer." (PMID 24040298, 2013). "Consequently, phosphorylated HK2 assists the cell growth and paclitaxel tolerance in breast cancer." (PMID 40612109, 2025). "Notably, HK2 is highly expressed in colorectal, liver and breast cancers." (PMID 39661501, 2024). "Notably, we also found that the regulation of miR‐143‐3p targeting of HK2 could affect tumor growth and the Warburg effect in breast cancer, which is similar to our results that miR‐143‐3p directly targets the HK2‐3'UTR binding site in glioma cells." (PMID 36708044, 2023). "In addition to its critical role in glycolysis and autophagy, HK2 also facilitates apoptosis resistance and the induction of chemo-resistance in pancreatic, epithelial ovarian and breast cancers by increasing its expression or dimerization and interaction with voltage-dependent anion channels." (PMID 37190124, 2023). "HK2 catalyzes the first committed step of glucose metabolism and initiates the major pathways of glucose utilization, it is confirmed to be a tumor promoter and plays an important regulating role in glucose metabolism in multiple malignancies, including breast cancer, lung cancer, and liver cancers." (PMID 36072431, 2022). "And the miR-591/HK2 axis could also regulate breast cancer apoptosis." (PMID 33658057, 2021). "Besides weakening mTOR activities, the reversal of chemoresistance was accompanied by enhanced mitochondrial-mediated apoptosis and the downregulation of hexokinase 2 (HK2) activities, therefore mediating cell death and preventing the metastatic behaviour of breast cancer cells, respectively." (PMID 34299604, 2021). "HK2, the first enzyme in the glycolytic pathway catalyzing the reaction in which glucose is phosphorylated into glucose‐6‐phosphate, has been identified overexpressed in numerous tumors, such as laryngeal carcinoma (Chen, Zhang, Li, Tang, & Kong, 2014) and breast cancer." (PMID 32533646, 2020). "In hypoxic breast cancer cells, oxidative stress-induced overexpression of miR-181c blocked HIF-1α accumulation and diminished hypoxia-inducible levels of glycolysis enzymes, including glycolysis-associated glucose transporter-1 (GLUT1), hexokinase 2 (HK2), PDK1, and lactate dehydrogenase A (LDHA)." (PMID 35006436, 2020). "However, in another study, a 24 h treatment of MDA-MB-231 cells with BA (up to 20 μM) did not alter lactate levels nor the expression of glycolytic enzymes, while BA-treated SK-BR-3 and MCF-7 breast cancer cells displayed decreased protein levels of hexokinase (HK2) and/or pyruvate kinase PKM2." (PMID 32784479, 2020). "For example, expression of hexokinase 2 (HK2), the embryonic isoform of hexokinase, the enzyme which defines the start of glycolysis, is associated with increased risk of recurrence, and adverse clinical outcome for breast cancer, pancreatic cancer, and neuroblastoma patients." (PMID 31921862, 2019).
breast cancer (continued). "Finally, we investigated whether there was any link between the expression of WSB1 and HIF targets SLC2A1, VEGFA, CA9, and HK2 in breast cancer patients." (PMID 29540773, 2018). "For instance, Hexokinase2 (HK2), an enzyme catalyzing the first committed step of glucose metabolism, has recently been shown to be required for tumor initiation and maintenance by using mouse models of KRas-driven lung cancer and ErbB2-driven breast cancer with Hk2 conditional knockout." (PMID 24318446, 2013). "The recent demonstration of human glandular kallikrein (hK2) expression in a breast carcinoma cell line has suggested that this putatively prostate-restricted, steroid hormone-regulated protease may also be expressed in breast epithelium in vivo and secreted into the mammary duct system." (PMID 10646889, 2000). "SNHG5 has also been shown to enhance glycolytic flux in breast cancer through the miR-299/BACH1 axis, promoting the expression of glycolytic enzymes such as HK2, PFK1, and GAPDH." (PMID 41550840, 2026). "In breast cancer, SNHG5 activates a metabolic reprogramming program by regulating BACH1 through miR-299, thereby upregulating glycolytic enzymes such as HK2 and PFK1, and promoting proliferation via enhanced aerobic glycolysis." (PMID 41550840, 2026). "Based on microarray data and immunohistochemical (IHC) analysis, HK2 protein expression was significantly correlated with HIF-1α immunoreactivity, Ki67 status and cancer recurrence in breast cancer patients." (PMID 41154605, 2025). "However, role of 2-DG in regulating pyroptosis, especially in breast cancer, where metabolic traits (e.g., elevated glycolysis) and subtype heterogeneity (e.g., higher hexokinase-2 (HK2) expression in triple-negative breast cancer) may alter responses, remains unclear." (PMID 41415273, 2025). "For example, in breast cancer, these two pathways enhance YAP transcriptional activity, promoting the expression of hexokinase 2 (HK2), which in turn increases cancer cell migration and invasion." (PMID 41450917, 2025). "In breast cancer (BC) cells, curcumin enhances sensitivity to 4-hydroxytamoxifen and induces apoptosis by inhibiting the SLUG/HK2 axis." (PMID 41515171, 2025). "For example, FOXD1 enhances the aerobic glycolysis process by increasing HK2, LDHA, and GLUT1 expression in breast cancer cells." (PMID 41214670, 2025). "HK2 has been shown to interact with mTOR and inhibit its activity in TAMR-MCF-7 breast cancer cells." (PMID 40303296, 2025). "Instead, this activation triggers a switch toward pro-death signalling by inhibiting HK2, thereby initiating GSDME-dependent pyroptosis in EMT6 and 4T1 murine breast cancer cells." (PMID 41415273, 2025). "Collectively, these findings demonstrated that 2-DG activates the cAMP/PKA pathway to suppress HK2 expression, thereby triggering caspase-3/GSDME-mediated pyroptosis in mouse breast cancer cells." (PMID 41415273, 2025). "The results of the GEPIA analysis revealed a correlation between TIGIT expression and the down-regulation of HK2 and LDHA in breast cancer tissues." (PMID 38216949, 2024). "circRNF20 can promote breast cancer cell proliferation and aerobic glycolysis through the circRNF20/miR-487a/HIF-1α/HK2 axis." (PMID 38408962, 2024). "Knockdown of circABCB10 led to decreased protein levels of glycolysis-related factors, such as HIF1a, HK2, and LDHA, resulting in enhanced radiosensitivity of breast cancer cells." (PMID 38408962, 2024). "Interestingly, in a conditional knockout mouse model, HK2 mediated KRas-driven lung carcinoma and ErbB2-driven generation and maintenance of breast cancer, and HK2 downregulation inhibited lung cancer in vitro and in vivo as well as the malignant biological behavior of breast cancer." (PMID 37854321, 2023).
breast cancer (continued). "Moreover, Hk2 supports neoplastic growth in glioblastoma multiforme, provides chemoresistance to epithelial cells of ovarian cancer, and initiates and maintains lung and breast cancer tumors in lung and breast mouse models, and its inhibition confers therapeutic effects." (PMID 37505851, 2023). "To further evaluate the effect of aerobic glycolysis in breast cancer angiogenesis regulated by CMA, we used HK2 siRNA transfection and evaluated the capacity of angiogenesis." (PMID 36913368, 2023). "In another study, circYY1 was found to upregulate the protein levels of HK2 and LDHA simultaneously in breast cancer cells and knockdown of circYY1 has a good tumor inhibitory effect." (PMID 37204526, 2023). "In contrast, in vesicles with high levels of miR-7641, miR-7641 inhibited HIF-1α to downregulate the levels of HK2, GLUT1, and LDHA to suppress glycolysis in breast cancer." (PMID 37204526, 2023). "BCAR4 acts together with the Hedgehog pathway effector GLI2 to upregulate HK2 and PFKFB3, which promotes proliferation and glucose uptake in breast cancer cells." (PMID 37204526, 2023). "However, the relationship between HK2 and immunoregulation in breast cancer remains unclear." (PMID 37377974, 2023). "HK2 and PKM2 were found to be upregulated in luminal B, whereas PFKM was overexpressed in the luminal A subtype of breast cancer." (PMID 35328104, 2022). "In the present study, the expression profiles of key metabolic genes (HK2, PFKM, and PKM2) were assessed in the breast cancer cohort of Pakistan using quantitative polymerase chain reaction (qPCR) and IHC." (PMID 35328104, 2022). "Oroxylin A suppresses the glycolysis-dependent proliferation of breast cancer MDA-MB-231 cells by activating SRT3, and decreasing HIF-1α-targeted HK2 gene transcription." (PMID 36339566, 2022). "The protein levels of HK2 and VDAC1 and the effects on the prognosis of breast cancer patients were analyzed based on online databases." (PMID 36186902, 2022). "Next, we explored the relationship between the expression of HK2 and VDAC1 and the prognosis of breast cancer patients." (PMID 36186902, 2022). "In PCOS, HK2 mediates glycolysis in KGN cells mediated by miR-143-3p and miR-155-5p, which is similar to the role of HK2 in breast cancer cells." (PMID 35534864, 2022). "Expression of glycolysis-related proteins, like HK2, LDHA, and PKM2, increases in breast cancer cells." (PMID 36188552, 2022). "Taken together, all these findings are indicative of the role of HK2, PKM2, and PFKM genes in tumor growth, proliferation, lympho-vascular invasion, and metastasis in breast cancer." (PMID 35328104, 2022). "An increase in overall survival and decreased tumor burden was seen upon HK2 deletion in KRAS-driven lung cancer and ERBB2 driven breast cancer." (PMID 35328104, 2022). "The results revealed that depletion of Zeb1 inhibited the expression and activity of HK2, PFKP and PKM2; however, ectopic Zeb1 expression had the opposite effect to enhance the glycolytic phenotypes in breast cancer cells." (PMID 35246504, 2022). "By inhibiting the activity of AKT, ursolic acid (UA) decreased the levels of HK2 and PKM2 in human breast cancer SK-BR-3 and MCF-7 cells." (PMID 36339566, 2022). "Knocking down of HK2, a gene downstream of YAP, in breast cancer cells MCF7 also inhibited the migration ability of the cells." (PMID 33718214, 2021). "miR-125a and miR-143 negatively regulate the levels of HK2 in hepatocellular carcinoma cells (HCC) and breast cancer cells." (PMID 33922649, 2021). "The role of miR-185 has been investigated in various cancers including lung cancer, osteosarcoma and breast cancer by targeting SOX9, HK2, DNMT1 and E2F6, respectively." (PMID 33507687, 2021). "For example, in human breast cancer tissues the positive correlation between CD68+ TAM infiltration and glycolytic enzyme expression GLUT1, GLUT3 and HK2 in cancer cells was demonstrated by immunostaining." (PMID 32486098, 2020).
breast cancer (continued). "Many tumor cells overexpress HK2, and preclinical mouse models of genetically engineered NSCLC (non-small cell lung cancer) and breast cancer demonstrate that HK2 inhibition delays tumor progression." (PMID 31790363, 2019). "To clarify the role of compression-induced upregulation of ENO2, HK2, or PFKFB3 genes in breast cancer progression, we investigated genetic alteration of the genes." (PMID 31428701, 2019). "The HIF-1α-inducible expressions of GLUT1, HK2, PDK1, and LDHA were low in NRF2-silenced breast cancer cells and, accordantly, levels of hypoxia-inducible glycolysis metabolites such as G6P, F16P, GAP, and lactate were diminished by NRF2-silencing." (PMID 31078780, 2019). "This conclusion was consistent with our experimental results that phosphorylation of HK2 by PIM2 enhanced glycolysis and contributed to the resistance of breast cancer cells to paclitaxel." (PMID 29985480, 2018). "Further, YAP/TEAD/p65 triplet synergistically upregulates hexokinase 2 (HK2) transcription, which promotes breast cancer cell migration." (PMID 28945218, 2017). "Co-culture significantly promoted breast cancer cell lung metastasis, and also increased the expression of CCR5, HK2 and p-AMPK in lung metastases." (PMID 29299159, 2017). "Recent reports have shown that TGF-β increased Glut1 expression and glucose uptake in the EMT transformed breast cancer MCF-7 cells; and Hexokinase 2 (HK2) was also increased in TGF-β-activated fibroblasts." (PMID 29137396, 2017). "The repression of AKT2 and HK2 is consistent with a previous report on the ability of acidosis to repress AKT and glycolysis in breast cancer cells." (PMID 23613998, 2013). "The initial rate-limiting enzymes of glycolysis, hexokinase 1 (HK1) and hexokinase 2 (HK2), are markedly overexpressed in breast cancer, with the suppression of HK expression leading to the dampening of breast cancer cell proliferation, invasion, and migration." (PMID 40165895, 2025). "Furthermore, 1,25(OH)2D treatment reduced the protein levels of hexokinase 2, an enzyme that plays a crucial role in the initial stages of glycolysis, in MCF-7 breast cancer cells, but increased hexokinase 2 protein expression in MDA-MB-231 cells." (PMID 39872372, 2025). "In breast cancer MCF7 cells and murine mammary 4T1 cells, 2DG inhibition of glycolysis occurs through ROS inhibition and a cell signaling feedback loop (2DG/ROS/PI3K/AKT/HIF1α/HK2/glycolysis)." (PMID 39251846, 2024). "This might be explained as circRNF20 acts as a miRNA-487a sponge; therefore, cirRNF20/miR-487a targets hypoxia inducible factor-1α(HIF-1α) in breast cancer cells, indicating HIF-1α supports the transcription of HK2." (PMID 37243750, 2023). "YY1 overexpression could reverse the decrease of glucose uptake, lactate production, ATP release, HK2, and LDHA proteins in circYY1 depletion breast cancer cells." (PMID 37060064, 2023). "In HeLa cells, AKT inhibitor IV (Ai4) serves to intensify the nuclear presence of HK2; conversely, in MDA‐MB‐231 breast cancer cells, Ai4 merely redistributes HK2 throughout the cytoplasm without inducing its nuclear accumulation." (PMID 38034101, 2023). "In breast cancer, the lncRNA BCAR4 was identified as a downstream target of YAP that controls cancer development, by reprogramming glucose metabolism through the transcription of two glycolysis activators, Hexokinase 2 (HK2) and PFKFB3." (PMID 37689702, 2023). "Carpesium abrotanoides L (CA) and mycoepoxydiene (MED) were reported to have anti-breast cancer role and could inhibited cervical cancer progression by suppressing the expression of glycolysis-related genes GLUT1 and HK2." (PMID 36339566, 2022).
breast cancer (continued). "Despite the decreased overall phosphoryl flux, overexpression of HK2, AK2, and AK6 isoforms within cell compartments could promote aggressive breast cancer growth." (PMID 35712500, 2022). "In addition, the expression of key glycolysis genes GLUT1, HK2 and PDK1 was detected in breast cancer cells overexpressing HIF-1α after HNK treatment." (PMID 35350760, 2022). "UALCAN analysis revealed that the protein level of HK2 was lower in breast cancer tissues compared with non-cancer tissues." (PMID 36186902, 2022). "Here, we show that ectopic Zeb1 directly increases the transcriptional expression of HK2, PFKP, and PKM2, which are glycolytic rate-determining enzymes, thus promoting the Warburg effect and breast cancer proliferation, migration, and chemoresistance in vitro and in vivo." (PMID 35246504, 2022). "Furthermore, the novel circRNF20 (hsa_circ_0087784) is expressed at high levels in breast cancer (BC), and promotes the proliferation and glycolysis of BC cells via the miR-487a/HIF-1α/HK2 axis." (PMID 35915091, 2022). "It was found in a model with breast cancer cells that circular RNA circRNF20 promotes the Warburg effect by harboring miR-487a and, thus, allows the HIF-1a-dependent expression of HK2 via the circRNF20/miR-487a/HIF-1α/HK2 axis." (PMID 33806538, 2021). "Notably, the effects of ETV4 knockdown on the mRNA expression of HK2 and PKM2 are different in HCC and breast cancer cells, suggesting a cancer type-specific regulation of these two enzymes by ETV4." (PMID 34052833, 2021). "ETV4 knockdown also downregulated HK2, LDHA and PDK1 protein levels in breast cancer cells." (PMID 34052833, 2021). "Also, siRNA-knockdown STAT3 in CRC cells decreased mRNA levels of HK2 by reducing STAT3 recruitment to HK2 promoter, consistent with the findings in breast cancer cells." (PMID 32273843, 2020). "Besides, breast cancer cells co-cultured with TAMs showed high expression of glycolytic enzymes, including GLUT3, HK2, PKM2 (pyruvate kinase isozyme M2) and LDHA." (PMID 32486098, 2020). "Notably, the introduction of a miR-181c inhibitor in NRF2-silenced breast cancer cells restored HIF-1α accumulation and HK2 elevation following hypoxic incubation." (PMID 31078780, 2019). "Also, high glucose consistently triggered HK2 and LDHA expression and stimulated the USP28/MYC axis in breast cancer cells." (PMID 30688660, 2019). "In addtion, the expression of HK2 also positively correlated with YAP in human breast cancer samples (Spearman’s correlation, r =0.581, P<0.001), indicating that YAP-mediated HK2 upregulation might exist in vivo." (PMID 28945218, 2017). "Furthermore, knockout of HK2 suppressed tumor initiation and progression in KRAS-driven lung cancer and ErbB2-driven breast cancer mouse models." (PMID 29043013, 2017). "And the absence of HK2 prevented breast cancer from metastasizing." (PMID 39991762, 2025). "As CCL2, HGF and CCL2/HGF treatment of breast cancer cells led to differences in glucose metabolism, we examined for expression of glycolytic proteins over time, including glucose transporter 1 (GLUT1) and rate limiting enzymes HK2, lactate dehydrogenase (LDHA) and pyruvate kinase M (PKM)." (PMID 40736024, 2025). "In basal-like and HER2-positive breast cancers, we demonstrated that a low WWOX/HIF1A ratio is particularly detrimental, as it triggers HIF1α-mediated upregulation of immunosuppressive mediators such as TLR4, NOTCH1, PTX3, and IL6R, alongside glycolytic enzymes like GLUT1 and HK2." (PMID 41007296, 2025). "Similarly, lncRNA SNHG5 directly targetsmiR-299 repression, upregulates BTB domain and CNC homology 1 (BACH1) transcription factor levels, and increases HK2 and PFK1, and lncRNA SNHG7 directly targets miR34a-5p to upregulate LDHA and promote glycolysis in breast cancer." (PMID 37204526, 2023).